ALB (albumin)
Diseases named in the same sentence as ALB in open-access papers (continued):
Sharing a sentence is not in itself a finding about the gene and the disease.
Ascites (continued). "In addition, albumin administration to cirrhotic patients with ascites has been shown to result in markedly reduced plasma renin activity, aldosterone levels and muscle sympathetic nerve activity in a number of patient types with ascites." (PMID 26606982, 2015). "Albumin, bilirubin, and ascites are the factors used to calculate the CP score." (PMID 24779518, 2014). "This complication may be effectively prevented with the administration of 8 g of human albumin/L of tapped ascites after the completion of large-volume paracentesis (>5 L)." (PMID 26237020, 2014). "In the present study, we excluded the patients with low blood albumin in order to exclude the nutritional factor related ascites, so in our study ascites might serve as an indicator of disseminative abdomen-pelvic metastasis." (PMID 23874550, 2013). "The association with BMI was independent of the presence of ascites, low albumin or the Child-Pugh score." (PMID 24490061, 2013). "Ascites did not subside even with albumin and Cabergoline; hence other causes of ascites were evaluated by Mantoux test and chest X-ray, which were negative for tuberculosis." (PMID 24167730, 2013). "Ascites, hyponatremia and low albumin were common in the infection group." (PMID 24137231, 2013). "Whereas MELD includes only objective laboratory parameters (the international normalized ratio [INR] of the prothrombin time, and serum bilirubin and creatinine), the CTP score includes both objective (INR, bilirubin, and albumin) and subjective components (ascites and encephalopathy)." (PMID 23349678, 2013). "Lastly, as regards oedema and/or ascites, it is difficult to model this variable, as assessing progression of this is difficult to measure, as compared with the continuous variables of serum bilirubin and albumin." (PMID 23984317, 2013). "The covariates consist of a treatment indicator, age, sex, 5 categorical variables (ascites, hepatomegaly, spider, edema, and stage of disease) and 9 continuous variables (bilirubin, cholesterol, albumin, urine copper, alkarine, SGOT, triglycerides, platelet count, and prothrombine)." (PMID 23112827, 2012). "An increase in serum albumin is one factor related to improving ascites." (PMID 23304539, 2012). "Therefore, albumin and ascites are important therapeutic targets in cirrhotic patients." (PMID 41149065, 2025). "Albumin was nonlinearly associated with ascites in patients with viral hepatitis." (PMID 40591542, 2025). "LVP with albumin substitution may be the first-line therapy for ascites; however, eligible patients must have an expected survival prognosis, and repeated paracentesis is required every 10–14 days in most patients, even if the entire volume of the ascitic fluid is drained." (PMID 38668394, 2024). "Therefore, the intake of BCAAs might be utilized for albumin synthesis, which reduces serum concentrations of albumin and results in the reduction of ascites degree." (PMID 37189711, 2023). "Additionally, assessing the patient profile for BMI, whether ascites was present, and other hemodynamic studies including albumin, PT/INR, and liver enzymes would indicate disease severity." (PMID 37795065, 2023). "Regarding the diminution of fatty acids and cholesterol in cirrhotic ascites relative to either postoperative drainage fluid or plasma, it is proposed that these observations can in part be interpreted in terms of the concentration and physicochemical properties of albumin." (PMID 35745058, 2022). "Besides LSR, baseline imaging features of peritumoral hypointensity in the hepatobiliary phase (descriptor of mVI), satellite lesions, ascites, and varices and baseline laboratory values of bilirubin, albumin, INR and ALBI score were correlated with deterioration in liver function during follow-up." (PMID 34686780, 2022). "In addition to the beneficial effects of albumin on renal perfusion, long-term administration of albumin may improve outcomes in patients with ascites." (PMID 33270161, 2021).
Ascites (continued). "The results from the ANSWER study have proven that intravenous treatment with human albumin improves the course of disease, with a lower incidence of almost all common complications and longer survival of patients with decompensated liver cirrhosis and pronounced ascites." (PMID 34836265, 2021). "However in C-P class A patients, with apparently normal liver functions, prognosis varies widely In addition, some of the variables in the C-P grade are interconnected (e.g., ascites and serum albumin levels), and the grading of ascites and encephalopathy can be highly subjective." (PMID 31191834, 2019). "Likewise, lower levels of platelets and albumin were found in patients who developed ascites." (PMID 24755710, 2014). "A previous study from our center showed that response-guided treatment with vasoconstrictors, albumin, and furosemide to maintain MAP >82 mmHg had better ascites control and improvement in AKI in acute on chronic liver failure patients." (PMID 39912014, 2025). "In patients with large ascites with hepato-renal syndrome-acute kidney injury (HRS-AKI), the addition of vasoconstrictors such as terlipressin or noradrenaline with albumin is the standard of care." (PMID 39912014, 2025). "Univariate analysis identified significant associations between 12-month TF mortality and variables such as age, sex, variceal bleeding, infection, ascites, MELD score, NHR, LHR, MHR, ALT, AST, ALB, and TC (all p < 0.05)." (PMID 39917063, 2025). "For example, consider a male patient with ascites, preoperative ICU stay history, 16-day ICU stay, albumin levels of 37 g/L, and total bilirubin levels of 491 μmol/L." (PMID 40281777, 2025). "The multivariate analysis identified significant predictors of ascites incidence, with odds ratios of 2.09 (95% CI 1.31–3.33, p < 0.01) for PVTT and 0.47 (95% CI 0.29–0.76, p < 0.01) for albumin level." (PMID 38583112, 2024). "The Child-Pugh score was calculated according to total bilirubin, albumin, INR, ascites status, and degree of hepatic encephalopathy." (PMID 38195397, 2024). "The PALBI score has the benefit of including the bilirubin and albumin levels, similar to the CTP score, while excluding potentially confounding and subjective parameters such as ascites and hepatic encephalopathy." (PMID 39027759, 2024). "In the training cohort, univariate analyses revealed that age, sex, GIB, SBP, OHE grade, ascites, MELD score, and levels of AST, ALT, TBIL, ALB, TC, HDL-C, LDL-C, Cr, NLR, PT, and PTA were prognostic factors for 1-year TF mortality (all p < 0.05)." (PMID 39200247, 2024). "CTP class is determined using albumin, bilirubin, INR, ascites, and encephalopathy whereas the MELD-Na score uses sodium, creatinine, bilirubin, and INR." (PMID 38966126, 2024). "Univariate analysis identified several variables, including serum albumin, Child-Pugh score, MELD score, ascites, NSBB use, BMI, VATI, TATI, and SATI, to be correlated with rebleeding." (PMID 38185678, 2024). "Baseline characteristics including age, gender, malignant etiology, presence of ascites, and preoperative prognostic nutritional index (PNI = 10 × albumin [g/dl] + [0.005 × lymphocytes/μl]) were equivalent in both groups." (PMID 37228709, 2024). "Paromomycin improved CPS by improving serum albumin levels, and neomycin improved CPS by improving ascites and HE." (PMID 36983211, 2023). "The clinical measures include total bilirubin, serum albumin, prothrombin time (PT)/international normalized ratio (INR), ascites, and hepatic encephalopathy." (PMID 37795065, 2023). "In contrast, we detected significant deterioration in liver functional reserve including albumin levels, Child–Pugh score, ALBI score, and the appearance of ascites within the initial 3 months of treatment." (PMID 36551574, 2022). "In competing risk regression, on-treatment LSM had prognostic value for hepatic decompensation during FU in analyses adjusted for either ascites, MELD or albumin." (PMID 35207727, 2022).
Ascites (continued). "At baseline, history of ascites, elevated INR, lower albumin levels, advanced Child‐Pugh score, elevated MELD and total bilirubin, and abnormal AST were associated with the risk of hepatic SAEs during OCA." (PMID 35932095, 2022). "The ranking into the three CP groups (A-C) is based on a point scale; the CP score is calculated based on three objective [serum albumin, serum bilirubin, and international normalized ratio (INR)] and two subjective (ascites and encephalopathy) parameters." (PMID 35463008, 2022). "This score combines albumin, the international normalized ratio (INR), bilirubin, ascites, and hepatic encephalopathy." (PMID 34638502, 2021). "The serum-ascites albumin gradient (SAAG) is a useful index in diagnosis of cirrhotic ascites, as SAAG ≥ 1.1 g/dL indicates that portal hypertension is involved in ascites formation with high accuracy." (PMID 34231046, 2021). "Age, male sex, serum albumin, MELD score, presence of ascites, alcohol vs. other etiology, LVEF, and E/e′ ratio were analysed by the Cox proportion hazard model." (PMID 34900353, 2021). "The calculation of the Child–Pugh score uses bilirubin, albumin, international normalized ratio (INR), ascites, and encephalopathy." (PMID 34204545, 2021). "When assessing the prognosis of patients with HH, clinical and biological factors (the severity of ascites, SBP, HRS, low serum albumin levels) appear to significantly influence mortality." (PMID 34441984, 2021). "For example, the Child–Pugh score contains five parameters (total bilirubin, albumin, INR, ascites, and hepatic encephalopathy), but the subjective natures for the assessments of ascites and encephalopathy have the propensity to reduce accuracy." (PMID 34055994, 2021). "Many potential parameters for poor prognosis in HBV-ACLF patients were defined, including advanced age, ascites, hepatic encephalopathy, high TBil, Cr, WBC, NEU, and INR levels and low ALB, ALT, Na, Cl, RBC, and PLT levels." (PMID 33336028, 2020). "This appears suitable to the fact of the several laboratory and clinical markers which count into Child score: albumin, INR, bilirubin, encephalopathy and ascites." (PMID 32107625, 2020). "Liver failure (LF) is defined as decompensation complications performing ascites, encephalopathy, and coagulopathy of any degree, and other physiological function of liver is damaged (e.g., AST, ALT, TBIL, and ALB)." (PMID 29686702, 2018). "Child-Pugh classification and evaluation of serum albumin,serum bilirubin, INR, ascites and encephalopathy also are performed." (PMID 29340553, 2017). "Child-Pugh assigns a score from 1 to 3 reflecting the severity of ascites, hepatic encephalopathy, international normalized ratio (INR) of prothrombin time, albumin and bilirubin." (PMID 26420028, 2015). "The current CTP classification is determined by serum albumin, bilirubin and international normalized ratio (INR) of prothrombin time (PT) levels, ascites formation and encephalopathy." (PMID 24906132, 2014). "Following PTA, ascites resolved, serum albumin normalized, and no further gastrointestinal bleeding occurred." (PMID 42088130, 2026). "Since he was 16 years old, he had multiple admissions for FC failure complicated by PLE and ascites, which did not respond to conventional treatments including diuretics, corticosteroids, albumin, and immunoglobulin infusions." (PMID 41836499, 2026). "Deceased patients were older, had a higher prevalence of variceal bleeding, infection, and ascites, and demonstrated elevated MELD scores, ALT, AST, TBIL, INR, Cr, NHR, LHR, and MHR levels, with significantly lower TC, ALB, LDL-C, and HDL-C levels (all p < 0.001)." (PMID 39917063, 2025). "Treatment eligibility hinges on hepatic reserve, so the Child-Pugh classification, comprising serum bilirubin, albumin, prothrombin time/international normalised ratio (INR), ascites, and hepatic encephalopathy, stratifies patients into classes A (5-6 points), B, or C." (PMID 41450371, 2025).
Ascites (continued). "Like an exudative pleural effusion, endometriosis-related ascites is typically bloody and protein-rich, with a low serum-ascites albumin gradient (SAAG), reflecting its inflammatory, non-portal hypertensive origin." (PMID 40918755, 2025). "There was heterogeneity within Child-Pugh B: Case 1 (B7) was driven primarily by low albumin (2.7 g/dL) rather than refractory ascites/encephalopathy, bearing different prognostic/tolerability implications." (PMID 41450371, 2025). "The CP has some disadvantages, including subjective factors (ascites and encephalopathy) and interrelated factors (serum albumin and ascites), and it was not established statistically." (PMID 39992725, 2025). "The CTP score includes five parameters: albumin, bilirubin, PT or INR, ascites, and hepatic encephalopathy, which have problems of subjective judgment and threshold definition, and may not accurately reflect the severity of liver disease." (PMID 38191888, 2024). "Usually, ESLD patients have ascites and general edema because the liver is not producing enough albumin protein to keep the water in circulation." (PMID 39131023, 2024). "Other variables already included in the prognostic models (ascites, hepatic encephalopathy, creatinine, total bilirubin, albumin, fT3, and fT4) were not included to avoid multicollinearity." (PMID 39420934, 2024). "Those indicators are, however, not ideal for cirrhotic patients: weight is not reliable because of the possible presence of ascites and edema, and albumin levels are chronically low due to synthesis diminution." (PMID 38561792, 2024). "Is the amount of ascites removed per day associated with the clinical outcome in patients with refractory ascites treated with tunneled-intraperitoneal catheters or Alfapump without albumin infusion?" (PMID 37410459, 2023). "Patients prescribed antibiotics without infection had similar age, gender, presence of ascites, and serum albumin to those not, but had significantly increased variceal bleeds, HE, creatinine, WCC, and CRP." (PMID 35970815, 2023). "The NAR ≥ 1.40 group had a significantly higher proportion of male, a higher incidence of infection, ascites, jaundice, and higher CRP, ALT, AST, TB, INR, WBC, Neutrophil, NAR, Cr, PLT, and MELD scores, but lower serum sodium and albumin than the NAR < 1.40 group." (PMID 38007536, 2023). "Except the ANSWER (Albumin for the Treatment of Ascites in Patients with Hepatic Cirrhosis) study, none of these have shown significant benefit." (PMID 38101419, 2023). "The diuretic treatment in cirrhotic patients and the complication of ascites marks not merely an augmented renal Zn elimination, nevertheless similar to condensing the serum albumin levels and compact volume of albumin to fix zinc." (PMID 37189711, 2023). "In this regard, the Prevention of Mortality with Long-Term Administration of Human Albumin in Subjects With Decompensated Cirrhosis and Ascites (PRECIOSA) trial (NCT03451292), which is currently recruiting, will hopefully improve the evidence base regarding long-term administration of albumin." (PMID 37511665, 2023). "The ALBI score has recently been employed to assess the hepatic functional reserve, and uses two objective serological markers, albumin and bilirubin, but not subjective factors, including ascites and encephalopathy, in contrast to the Child–Pugh grade." (PMID 36230773, 2022). "Albumin, bilirubin, alkalin phosphatase (ALP), albumin to platelet ratio, albumin to ALP ratio, Child-Pugh classification, albumin-bilirubin (ALBI) grade, model for end-stage liver disease (MELD) and ascites have been shown as independent prognostic factors for QoL." (PMID 35008343, 2021). "The Child–Pugh grade takes into account albumin, PT/INR, ascites, and hepatic encephalopathy, but some of these factors are highly subjective, such as the severity of ascites and degree of hepatic encephalopathy, which may affect assessment ability." (PMID 34666694, 2021).
Ascites (continued). "Atkinson and Losowsky also found that no patient with liver cirrhosis developed ascites when the albumin serum level was within the normal range (above 3.7 g/dL)." (PMID 34281177, 2021). "The univariate analysis results indicated that factors significantly associated with better OS included sex (male), ECOG PS 0, no peritoneal metastasis, no ascites, high serum albumin levels, and GPS-L status." (PMID 33635904, 2021). "In contrast to the Child–Pugh grade, the ALBI grade uses only two objective serological markers, albumin and bilirubin, and subjective factors such as ascites and encephalopathy are not included." (PMID 34666694, 2021). "The CTP included bilirubin, albumin, INR, ascites, and encephalopathy." (PMID 34319020, 2021). "Ten years later, Losowsky and Atkinson clearly established that in order not to develop ascites, the albumin serum concentration has to be above 3.7 g/dL." (PMID 34281177, 2021). "All patients with liver decompensation were hospitalized and managed according to the standard of care (diuretics and albumin in the case of ascites, non-absorbable disaccharides for encephalopathy)." (PMID 32272656, 2020). "A few studies have shown that paracentesis under cover of intravenous albumin is feasible in patients with spontaneous bacterial peritonitis and tense ascites without any increase in mortality." (PMID 32704299, 2020). "ALB infusion amount exhibited weak positive correlation with ascites, and weak negative correlation with positive germiculture in abdominal drainage." (PMID 32293409, 2020). "By comparison, the Italian Association for the Study of the Liver (AISF) suggested that albumin could decrease the incidence of grade III and IV type C overt HE in cirrhotic patients with ascites." (PMID 31596729, 2019). "In recent years, however, the new albumin–bilirubin (ALBI) grade, which is used for evaluating liver function without peritoneal effusion and encephalopathy and bases the assessment on albumin and bilirubin levels only, has been proposed." (PMID 29765560, 2018). "It used five parameters: total bilirubin, serum albumin, INR, ascites, and encephalopathy." (PMID 29686702, 2018). "Clinical trials in Japan confirmed the efficacy of tolvaptan for refractory ascites regardless of serum albumin level, and the safely of a 14-day dosage regimen." (PMID 28362879, 2017). "As the Child-Pugh score includes serum albumin, PT, and ascites, they were not entered into the multivariate analysis, and because BMI significantly correlated with SMI, it was also excluded in the multivariate analysis to avoid the effect of collinearity." (PMID 28604642, 2017). "We found that there were lower levels of total protein and albumin, lower albumin/globulin ratio, lower body weight and higher spleen weight and ascites volume in cirrhotic rats with than without BT." (PMID 28134306, 2017). "Higher levels of CA-125 were found in BCS patients with abnormal hepatic function and low serum albumin levels and in patients with high volume of ascites compared to patients without these abnormalities." (PMID 26451141, 2015). "Oral BCAA supplementation helped to maintain liver reserve with higher serum albumin (SMD = 0.234, 95 % CI: 0.033–0.435, P = 0.022), and lower rates of ascites (RR = 0.545, 95 % CI: 0.316–0.938, P = 0.029) and edema (RR = 0.494, 95 % CI: 0.257–0.952, P = 0.035) than in the control group." (PMID 26155840, 2015). "In conclusion, patients receiving BCAA supplementation had a stronger functional liver reserve with higher serum albumin and lower rates of ascites and edema than those receiving no BCAA supplementation." (PMID 26155840, 2015). "Patients with good hepatic reserve, no ascites, and a good nutritional status (Child class A) can withstand surgery, whereas those with jaundice, low serum albumin, ascites, and muscle wasting have a higher operative mortality and postoperative morbidity." (PMID 26486859, 2015).